EEIG1 (estrogen-induced osteoclastogenesis regulator 1)
Description:
Key component of TNFSF11/RANKL- and TNF-induced osteoclastogenesis pathways, thereby mediates bone resorption in pathological bone loss conditions (By similarity). Required for TNFSF11/RANKL-induced osteoclastogenesis via its interaction with TNFRSF11A/RANK, thereby facilitates the downstream transcription of NFATC1 and activation of PLCG2 (By similarity). Facilitates recruitment of the transcriptional repressor PRDM1/BLIMP1 to the promoter of the anti-osteoclastogenesis gene IRF8, thereby resulting in transcription of osteoclast differentiation factors (By similarity). May play a role in estrogen action.
Synonyms: C9orf132; FAM102A; bA203J24.7; SYM-3A
Tractability: PROTAC: ubiquitination databases record sites on it.
Gene: Protein-coding gene on chromosome 9 (127,940,582 to 127,981,068, reverse strand). Ensembl gene ENSG00000167106.
Subcellular location: Nucleus; Cytoplasm; Membrane raft
Subcellular location (Human Protein Atlas): Cytosol
Gene Ontology:
Molecular function: protein binding
Biological process: positive regulation of osteoclast differentiation
Cellular component: cytoplasm; membrane raft; nucleus
Genetic constraint (gnomAD): Loss-of-function variants: 20 observed, 38.26 expected, observed/expected ratio (o/e) 0.52, 90% interval 0.37 to 0.76. The upper end of that interval is the gene's LOEUF score, 0.76, which puts it in group 3 of 6, group 1 being the genes least tolerant of losing a copy. Missense variants: 411 observed, 502.76 expected, observed/expected ratio (o/e) 0.82, 90% interval 0.75 to 0.89. Synonymous variants: 228 observed, 204.74 expected, observed/expected ratio (o/e) 1.11, 90% interval 1 to 1.24.
Homologues: Orthologues: chimpanzee EEIG1 (99% identical), macaque EEIG1 (99% identical), mouse Eeig1 (96% identical), guinea pig EEIG1 (96% identical), dog EEIG1 (95% identical), rabbit EEIG1 (93% identical), rat Eeig1 (86% identical), tropical clawed frog eeig1 (79% identical), zebrafish eeig1b (76% identical), pig EEIG1 (75% identical), zebrafish eeig1a (61% identical). Paralogues in human: EEIG2 (58% identical).
Diseases named in the same sentence as EEIG1 in open-access papers:
EEIG1 is named in the same sentence as 11 diseases in open-access papers, as found by Europe PMC text mining. Sharing a sentence is not in itself a finding about the gene and the disease. The quoted sentences say what the papers report.
infarction (1 paper, 2025). A localised pathological necrosis of tissue resulting from obstruction of the blood supply usually by a thrombus, an embolus, or vascular torsion. "EEIG1: also known as FAM102A, it is also overexpressed in the uremia group with infarction (logFC = 1.6695) and is involved in the positive regulation of osteoclast differentiation." (PMID 40332370, 2025).
EEIG1 also shares sentences with these, for which no sentence is quoted: breast carcinoma (2 papers); cancer (2); eye disorder (1); glaucoma (1); glioma (1); infection (1); Osteopenia (1); osteoporosis (1); tumor (1); uremia (1).